PIWIL1 (piwi like RNA-mediated gene silencing 1)
Diseases named in the same sentence as PIWIL1 in open-access papers (continued):
Sharing a sentence is not in itself a finding about the gene and the disease.
lung carcinoma (continued). "Also, PIWIL1 expression is elevated in lung cancer cell lines compared to normal lung epithelial cells." (PMID 22591718, 2012). "However, nothing is known about the role of PIWIL1 in lung cancer cells, making this an interesting gene for further study." (PMID 22591718, 2012). "Thus, one potential mechanism through which RASSF1C could potentially promote lung cancer metastasis is through regulation of the PIWIL1-piRNA axis." (PMID 36826019, 2023). "Notably, RASSF1C, known as an oncogene, was reported to regulate Piwil1 in lung cancer." (PMID 34295823, 2021). "We have identified PIWIL1 as a potential regulator of Beta-catenin gene expression and have identified specific piRNAs that appear to function as oncogenes (piR-34871 and piR-52200) and tumor suppressor (piR-35127 and piR-46545) in normal and lung cancer cells." (PMID 33227088, 2020). "Therefore, it was suggested that the PIWIL1 gene could be considered as a molecular target for the treatment of lung cancer, and the use of the PIWIL1 gene silencing technology is considered as a promising treatment." (PMID 31890151, 2019). "However, limited studies have explored the function of these EECTGs in cancer.Piwi like RNA‐mediated gene silencing 1 (PIWIL1), a lung cancer EECTG in our previous study, is the member of PIWI family and can bind to PIWIL‐interacting RNAs (piRNAs) during spermatogenesis." (PMID 29168346, 2018). "Thus, RASSF1C, IGFBP-5, PIWIL1, and the Wnt pathway could function together as a new axis that impacts lung cancer cell growth and progression." (PMID 25007054, 2014). "Hence, we wanted to assess the effect of BA on PIWIL1 gene expression in lung cancer cells." (PMID 25007054, 2014). "This research presents us the RASSF1C/PIWIL1/piRNA axis, modulating the Gem Interacting Protein (GMIP) mRNA expression by DNA methylation in lung cancer, and thus affecting the migration of cancer cells." (PMID 36882835, 2023). "In lung cancer, RASSF1C, a major member of the RASSF1 gene family, can encourage the expression of PIWIL1, as well as the modulation of piRNA’s expression." (PMID 36882835, 2023). "In lung cancer, IGFBP5 counteracted RASSF1C-induced ERK1/2-dependent stimulation of the stem cell gene Piwi like RNA-mediated gene silencing 1 (PIWIL1) resulting in re-sensitization of tumor cells to the anti-cancer drug betulinic acid." (PMID 36093095, 2022). "Over-expression of RASSF1C and knocking down RASSF1C and PIWIL1 modulated DNA methylation of genomic regions; and statistically significant candidate genes residing DMR regions in lung cancer cells were identified, including oncogenes and tumor suppressors." (PMID 33227088, 2020). "We have previously demonstrated that RASSF1C over-expression up-regulates PIWIL1 gene expression and thus we wanted to determine if RASSF1C over-expression would reduce the anti-proliferative effects of BA on lung cancer cells." (PMID 25007054, 2014). "We have shown that RASSF1C up-regulates PIWIL1 expression, and others have shown that RASSF1C enhances the accumulation of β-catenin protein levels in A549 lung cancer cells." (PMID 25007054, 2014). "Thus, we have chosen PIWIL1 for further investigation for reasons that it may have important functions in cancer stem cell initiation, maintenance, or progression as nothing is known about the function of this interesting gene in lung cancer." (PMID 22591718, 2012). "In this regard, we have illustrated that RASSF1C modulates the expression of the PIWIL1-piRNA gene axis suggesting the hypothesis that a RASSF1C-PIWI-piRNA pathway could potentially be a driver pathway that promotes lung cancer cell growth and progression." (PMID 33227088, 2020). "Existing studies mainly focused on the aberrant expression of PIWIL1 in tumors; however, the biological role of PIWIL1 in lung cancer has never been elucidated." (PMID 29168346, 2018).
lung carcinoma (continued). "The current findings further support our working hypothesis that PIWIL1 and piRNA are downstream targets of RASSF1C and suggest a novel mechanism in lung cancer oncogenesis and progression." (PMID 28423657, 2017). "Modulation of PIWIL1 and piRNA gene expression by RASSF1C is potentially a novel and important mechanism that may contribute to lung cancer stem cell development and progression." (PMID 28423657, 2017). "We then further focused on validating the modulation of PIWIL1 gene expression in lung cancer cells over-expressing RASSF1C using immunostaining and Western blot analyses, we also found that silencing of RASSF1C resulted in reduction of PIWIL1 expression." (PMID 22591718, 2012). "This leads us to the hypothesis that RASSF1C may play a role in early lung cancer initiation and progression through the activation of ERK1/2 and deregulation of PIWIL1 gene expression in lung cancer stem cells." (PMID 22591718, 2012). "In light of these findings, we assessed the impact of over-exprssing of piR-35127 and piR-46545 on lung cancer cell migration/inavsion and found that they drastically reduce wildtype lung cancer cell invasion as well as lung cancer cells overexpressing RASSF1C or PIWIL1." (PMID 36826019, 2023). "We found overexpressing PIWIL1, like RASSF1C, promotes lung cancer cell migration/invasion and that PIWIL1 overexpression resulted in increased expression of P4HA2, PLOD2, and collagen I protein levels suggesting that PIWIL1 could play a role TME remodeling." (PMID 36826019, 2023). "Interestingly, we found that co-expression of RASSF1C and IGFBP-5 reduced PIWIL1 mRNA and protein levels in lung cancer cell lines, while co-expression of RASSF1A-RASSF1C did not have a major effect on PIWIL1 mRNA levels compared to cells over-expressing RASSF1C." (PMID 25007054, 2014).
glioma (17 papers, 2012 to 2025). A benign or malignant brain and spinal cord tumor that arises from glial cells (astrocytes, oligodendrocytes, ependymal cells). "Furthermore, in glioma, breast cancer and sarcomas, in vitro studies have shown that the suppression of PIWIL1 caused inhibition of cell growth by different mechanisms." (PMID 25742785, 2015). "Decreased activity of PIWIL1 in glioma cells led to suppressed cell proliferation, increased apoptosis, altered expression of p21, cell cycle arrest at G0/G1, and increased and decreased expression of Bcl-2 and Bax, respectively." (PMID 39596284, 2024). "Invasion and migration of glioma cells were altered after inhibition of PIWIL1, supposedly by reducing the expression of MMP-2 and MMP-9." (PMID 39596284, 2024). "PIWIL1 has been proposed as a progression marker for both cervical squamous cell carcinoma and glioma, with expression levels correlated to tumor grades in these cancers." (PMID 39596284, 2024). "PIWIL1 maintains self-renewal and survival of glioma stem cells by regulating expression of related genes." (PMID 35003260, 2021). "Recently, it was shown that PIWIL1 is enriched in glioma stem-like cells (GSCs) and silencing PIWIL1 in GSCs impaired their self-renewal and triggered senescence or apoptosis." (PMID 33718392, 2021). "piRNA-DQ593109/PIWIL1 promotes therapeutic agent delivery into the glioma micro-environment, enhancing anti-tumor effects." (PMID 31399034, 2019). "piRNA-DQ593109/ PIWIL1 in glioma endothelial cells increased blood-tumor barrier (BTB) permeability by binding to maternally expressed 3(MEG3) lncRNA of the MEG3/miR-330-5p/RUNX3 axis." (PMID 31399034, 2019). "MiR-154-5p directly targets PIWIL1 and decreases its expression in glioblastoma and glioma." (PMID 33718392, 2021). "miR-154-5p is downregulated in glioma and targets PIWIL1 to suppress tumor growth and metastasis." (PMID 33195697, 2020). "PiR-598, piR-8041, piR-DQ590027, piR-DQ593109, PIWIL1, PIWIL2, PIWIL3, and PIWIL4 may all be involved in the pathogenesis of glioma, and could be diagnostic markers for glioma." (PMID 33109195, 2020). "Afterward, PIWIL1 could maintain self-renewal and survival of glioma stem cells." (PMID 38023199, 2023). "Knockdown of PIWIL1 could inhibit cell proliferation and induce apoptosis in glioma cells." (PMID 38023199, 2023). "Further, a study has found that the PIWIL1/piRNA-DQ593109 (piR-DQ593109) complex is a major regulator of blood-tumor barrier (BTB) permeability in glioma through the MEG3/miR-330-5p/RUNX3 axis, and their inhibitions could enhance efficient delivery of anti-glioma drugs to glioma tissues." (PMID 36009578, 2022). "Functional studies confirm that PIWIL1 and PIWIL2 frequently act as oncogenic drivers in cancers such as glioma, lung, and colorectal carcinoma." (PMID 40725379, 2025). "PIWIL1 also regulates apoptosis and cell cycle progression through P21, Cyclin D1, BCL-2 and BAX, and migration through expression of MMP-2 and MMP-9 in glioma cells." (PMID 31443431, 2019). "PIWIL1 and piR-DQ593109 were over-expressed in glioma-derived GECs." (PMID 33109195, 2020). "Moreover, silencing PIWIL1 by siRNA could inhibit the expression of BCL2 and cyclin D1 and suppress cell proliferation by facilitating apoptosis in glioma cells." (PMID 35003260, 2021).
endometrial cancer (16 papers, 2012 to 2026). Primary or metastatic malignant neoplasm involving the endometrium (mucous membrane that lines the endometrial cavity). "Studies have reported that increased expression of the PIWIL1 gene is associated with various cancers such as endometrial cancer, cervical squamous cell carcinoma, colon cancer, and hepatocellular carcinoma." (PMID 38012622, 2023). "In another female tumor, endometrial cancer, PIWIL1 caused the silence of PTEN expression through DNMT1-mediated hypermethylation." (PMID 35637965, 2022). "In endometrial cancer, PIWIL1 has been associated with EMT and cancer stem cell-like characteristics." (PMID 33718392, 2021). "PIWIL1 causes epigenetic silencing of PTEN gene via the upregulation of DNA methyltransferase DNMT1 in endometrial cancer cells." (PMID 33718392, 2021). "We further investigated the association between Piwil1 expression and clinicopathological features in endometrial cancer patients." (PMID 26506848, 2015). "In melanoma, endometrial cancer, mature B-cell neoplasms, non-small cell lung cancer, colon cancer, bladder cancer, invasive breast cancer, esophagogastric adenocarcinoma and head and neck cancer, PIWIL1 is often mutated." (PMID 33718392, 2021). "We found that the percentage of methylated CpG dinucleotides in Ishikawa, RL95–2 and HEC-1B was 45.83, 40.00 and 86.67%, respectively, suggesting that the reactivation of PIWIL1 expression in endometrial cancer is associated with hypomethylation of the PIWIL1 promoter." (PMID 32503542, 2020). "Consistently, we found a significantly positive correlation between Piwil1 expression and lymphovascular space involvement, lymph node metastasis, varying depth of myometrial invasion and advanced disease stage, all of which are associated with high risk factors in endometrial cancer." (PMID 26506848, 2015). "In endometrial cancer, PIWIL1 overexpression resulted in increased migration and invasiveness of tumor cells." (PMID 39596284, 2024). "In functional assays, PIWIL1 promoted cell viability, tumor sphere formation in vitro and tumorigenesis in vivo in cervical and endometrial cancer and glioblastoma." (PMID 38303021, 2024). "PIWIL1 overexpression in endometrial cancer cells promoted migration and invasion, possibly by inducing EMT." (PMID 38303021, 2024). "Endometrial cancer cells with low PIWIL1 expression have upregulated E-cadherin, while Vimentin and N-cadherin were down-regulated." (PMID 38031146, 2023). "PIWIL1 acts as an oncogene in endometrial cancers, inducing EMT and conferring stemness characteristics on EC cells, promoting cancer growth." (PMID 38031146, 2023). "In endometrial cancer cells, estrogen E2 induces ERα to bind to the PIWIL1 promoter, leading to hypomethylation of the promoter, which then upregulates PIWIL1 transcription." (PMID 38031146, 2023). "What is more, PIWIL1 was much more abundant in endometrial cancer tissues compared with atypical hyperplasia and normal tissues." (PMID 36212439, 2022). "PIWIL1 can drive EMT in endometrial cancer cells by upregulating the expression of Vimentin and N-cadherin and by decreasing E-cadherin expression." (PMID 33718392, 2021). "Another study observed that the protein levels of PIWIL1 increase in a stepwise manner in normal endometrium, endometrial atypical hyperplasia and endometrial cancer tissues." (PMID 33718392, 2021). "In endometrial cancer cells, estrogen was shown to enhance the transcription of PIWIL1 by facilitating the binding of the ERα to the PIWIL1 promoter." (PMID 33718392, 2021). "Several studies have shown that PIWIL1 is overexpressed in various types of cancer, such as lung and endometrial cancer." (PMID 34200970, 2021). "To understand why PIWIL1 is activated in endometrial cancer, we examined the methylation status of PIWIL1 promoter in Ishikawa, RL95–2 and HCE-1B cells." (PMID 32503542, 2020). "The ERα had a positive correlation with PIWIL1 in endometrial cancer tissue (r = 0.8, ****p < 0.0001)." (PMID 32503542, 2020).
endometrial cancer (continued). "In our previous study, we found that the expression of PIWIL1 was higher in ERα-positive endometrial cancer cell lines and tissues." (PMID 32503542, 2020). "In the present study, for the first time, we wanted to elicit the potentially molecular mechanism involved in regulating the expression of PIWIL1 in endometrial cancer." (PMID 32503542, 2020). "Herein, we demonstrate a novel molecular mechanism by which estrogen-ERα signaling and DNA hypomethylation co-regulate PIWIL1 expression in endometrial cancer." (PMID 32503542, 2020). "In our study, PIWIL1 immunoreactivity was mainly observed in ERα-positive endometrial cancer tissues." (PMID 32503542, 2020). "In summary, the study presented here demonstrates a novel molecular mechanism by which estrogen-ERα signaling and DNA hypomethylation co-regulate PIWIL1 expression in endometrial cancer." (PMID 32503542, 2020). "Collectively, these experiments strongly indicate that PIWIL1 is a key effector of the estrogen-induced cell growth in endometrial cancer." (PMID 32503542, 2020). "We first utilized different concentrations of E2 (10− 10 ~ 10− 8 mol/L) to stimulate three endometrial cancer lines and analyzed the expression of PIWIL1 at different times (24 h, 48 h, 72 h)." (PMID 32503542, 2020). "In ERα-positive endometrial cancer cells, we demonstrated that estrogen-ERα signaling significantly up-regulated the expression of PIWIL1, which was mediated by binding of the ERα onto the PIWIL1 promoter." (PMID 32503542, 2020). "Then the mRNA expression levels of ERα and PIWIL1 were measured by RT–qPCR in 30 endometrial cancer samples." (PMID 32503542, 2020). "Taken together, these results further suggest there is a relationship between PIWIL1 and estrogen-ERα signaling in endometrial cancer." (PMID 32503542, 2020). "In our previous study, we found that PIWIL1 was silenced in normal endometrium and reactivated in endometrial cancer." (PMID 32503542, 2020). "The expression of PIWIL1 and ERα in endometrial carcinoma tissues were investigated using immunohistochemistry and RT-qPCR." (PMID 32503542, 2020). "PIWIL1 promotes endometrial cancer stem cell development through endometrial EMT as over-expression of PIWIL1 increases N-cadherin and vimentin and decreases E-cadherin gene expression." (PMID 30719208, 2019). "Specific knockdown or overexpression of Piwil1 in endometrial cancer cell lines led to changes in tumor growth and metastatic potential in vitro and in vivo." (PMID 26506848, 2015). "In this study, we confirmed that the expression of Piwi proteins (Piwil1, Piwil2, Piwil13, and Piwil4) are different in endometrial cancer cell lines and we mainly focused on the role of Piwil1 in endometrial cancer." (PMID 26506848, 2015). "We found that the normal endometrium produces weak levels of Piwil1, but that Piwil1 was extensively detected in endometrial cancer, which is in accordance with reports." (PMID 26506848, 2015). "RT-qPCR, western blot and immunofluorescence were performed to assess the expression of Piwil1 in endometrial cancer cell lines." (PMID 26506848, 2015). "Although several studies have investigated the expression of Piwil1 in solid cancers, including endometrial cancer, this is the first study to address the function of Piwil1 in human endometrial cancer." (PMID 26506848, 2015). "Compared with atypical hyperplasia and normal tissues, Piwil1 was much higher in endometrial carcinoma tissues." (PMID 26506848, 2015). "Moreover, PIWIL1 has been implicated in regulating EMT and promoting stem-like characteristics in endometrial cancer cells." (PMID 41596471, 2026). "The authors suggest that the PIWIL1/DNMT1/PTEN signaling axis may play an important role in the progression of type I endometrial cancer." (PMID 39596284, 2024). "PIWIL1 was revealed to be responsible for the regulation of the PTEN gene in endometrial cancer." (PMID 39596284, 2024).